IL7 (interleukin 7)
Diseases named in the same sentence as IL7 in open-access papers (continued):
Sharing a sentence is not in itself a finding about the gene and the disease.
scrub typhus (1 paper, 2012). Scrub typhus is a rare dust mite-borne infectious disease caused by the Orientia tsutsugamushi bacterium and characterized clinically by an eruptive fever which is potentially serious. "The contradictory finding of increased apoptosis and proliferation of T cells in the peripheral blood of scrub typhus patients prompted us to measure the levels of IL-7 and IL-15, which potently induce the survival and proliferation of T cells." (PMID 22905277, 2012). "To investigate the potential mechanisms of the rapid turnover and proliferation of T cells in scrub typhus patients, we measured the amount of soluble IL-7 and IL-15 in the serum of patients since these cytokines induce the proliferation of and enhance the survival of T cells in mice and humans." (PMID 22905277, 2012).
septic peritonitis (1 paper, 2016). Septic peritonitis is an inflammatory condition of the peritoneum that occurs secondary to microbial contamination. "In this study, we tried to investigate the correlation of TLR9 expression with IL-17 production in PMNs during septic peritonitis and found that both sTLR9 and IL-7 could be expressed in the PMNs infiltrated into the peritoneal cavity of the mice infected with E. coli." (PMID 27057095, 2016).
sexually transmitted infections (1 paper, 2021). "Our results highlight the potential of IL-7 as a potent mucosal adjuvant to stimulate the FGT immune system and elicit vaginal antibody responses to local immunization, which is the most promising way to confer protection against many sexually transmitted diseases." (PMID 33717097, 2021).
skin inflammatory disease (1 paper, 2023). "Consequently, our research demonstrates that IL-7 has the potential to be used as a therapeutic approach for managing inflammatory skin diseases, such as AD." (PMID 37373104, 2023). "Based on these promising findings, we investigated whether IL-7 plays a role in another skin inflammatory disease, AD." (PMID 37373104, 2023).
squamous cell carcinoma (1 paper, 2019). A carcinoma arising from squamous epithelial cells. "Adenocarcinomas (ADC) of the gastrointestinal tract had significantly higher IL-7 concentration in tumor tissue than squamous cell carcinomas (SCC) by 1.7-fold." (PMID 31185636, 2019).
Ss (1 paper, 2018). "We hypothesized that Ss infection would be associated with alterations in memory T cell subset distribution, alterations that could be reflective of changes in IL-2, IL-4, IL-7, IL-9 and IL-15." (PMID 29795573, 2018).
strongyloidiasis (1 paper, 2025). An infection that is caused by nematodes of the genus Strongyloides, most commonly Strongyloides stercoralis, which is a soil-transmitted helminth, and which is characterized by a variety of gastrointestinal, dermatologic, and, occasionally, pulmonary manifestations. "IL-7, and other growth factors like FGF, was shown to be increased in patients treated for strongyloidiasis, suggesting its involvement in parasite elimination." (PMID 40407653, 2025).
syphilis (1 paper, 2017). A contagious bacterial infection caused by the spirochete Treponema pallidum. "We prospectively recruited all patients with a new diagnosis of syphilis and tested their plasma for IFNα, IFNγ, IL-1β, IL-12p40, IL-12p70, IP-10, MCP-1, MIP-1α, MIP-1β, IL-4, IL-5, IL-6, IL-7, IL-8, IL-10 and IL-17A at baseline pre-treatment and 6 months following therapy." (PMID 28143443, 2017).
systemic vasculitis (1 paper, 2005). "Although serum was not available from our cohort of solid tumour patients, we found high circulating levels of IL-7 in lymphodepleted patients with other tumours and with systemic vasculitis, which is in keeping with the literature." (PMID 15642146, 2005).
Thrombocytosis (1 paper, 2012). Increased numbers of platelets in the peripheral blood. "Elevated levels of IL-7, conversely, have been previously shown to be involved in thrombocytosis." (PMID 23284941, 2012).
thymic lymphoma (1 paper, 2022). "However, we previously showed that IL-9 alone did not promote thymocyte proliferation, while in combination with IL-7, it synergistically enhances cell proliferation, and may activate the JAK-STAT pathway during thymic lymphoma development." (PMID 35336821, 2022).
thyroid cancer (1 paper, 2015). "The role of IL-7 in relation to thyroid cancer remains largely unknown." (PMID 26274317, 2015).
thyroid diseases (1 paper, 2020). "Serum level of IL-6, IL-7, IL-10, and IL-13 was higher in thyroid disease, while IL-8 was lower than healthy controls." (PMID 32655554, 2020). "Serum levels of IL-7, IL-10, and IL-13 are higher in thyroid diseases than healthy controls." (PMID 32655554, 2020).
trauma (1 paper, 2023). "Levels of IFN-γ, IL-5, IL-7 were not different between trauma patients and healthy controls." (PMID 37120600, 2023).
trichomoniasis (1 paper, 2011). An infection that is caused by Trichomonas. "Incontrast, IL-12, IL-7, IL-10, IL-3, and IL-4 were increased in BV when comparedto control samples but not in trichomoniasis." (PMID 21572958, 2011). "For exampleMIP-1α, VEGF and MPO levels were significantly different than controls inChlamydia and trichomoniasis but not BV while in contrast,IL-6, IL-10, GM-CSF, G-CSF, IL-3, IL-7 and IL-12 were significantly changed inChlamydia and BV but not trichomoniasis." (PMID 21572958, 2011).
tuberous sclerosis (1 paper, 2017). Hereditary disease characterized by seizures, intellectual disability, developmental delay, and skin and ocular lesions. "Extrinsic IL-7 survival signal maintains naïve T cell quiescence, a mechanism that relies on tuberous sclerosis (TSC) function to keep mTOR activation in check." (PMID 28443090, 2017).
tubular adenoma (1 paper, 2017). A usually polypoid neoplasm arising from the glandular epithelium. "Detailed analysis revealed that IL-7 elevation coincided exclusively with villous growth pattern, while systemic IL-7 in patients with tubular adenomas was similar to controls." (PMID 27866242, 2017).
tularemia (1 paper, 2023). Tularemia is an infection caused by the bacterium Francisella tularensis. "Specifically, IL-2, MIP-1β, TNF, and IL-7 all fulfilled the criterion and the former three of these cytokines have previously been observed to correlate the control of infection in a human co-culture model and also in an animal models of tularemia." (PMID 37781364, 2023).
urolithiasis (1 paper, 2024). Stone(s) within the urinary tract. "Urolithiasis also impacts the expression of cytokines such as IL-2, CTACK, IL-5, IL-7, IL-8, GRO-α, MIG, and MIP-1α." (PMID 39021826, 2024).
uterine disease (1 paper, 2022). "While the role of IL-7 signaling in bovine pregnancy warrants further investigation, altered IL-7 signaling in the endometrium may be impacting immune cell dynamics and reducing maternal immune tolerance of the conceptus in cows after uterine disease." (PMID 35358206, 2022).
uterine infection (1 paper, 2022). "Interestingly, five discordant canonical pathways were uniquely affected by pregnancy following uterine infection, including iNOS signaling, Toll-like receptor signaling, and IL-7 signaling pathway (P < 0.05)." (PMID 35358206, 2022). "Interestingly, IL-7 signaling was identified as a discordant pregnancy affected pathway in cows following uterine infection that was not identified in healthy cows." (PMID 35358206, 2022).
uveitis (1 paper, 2025). An inflammatory process affecting a part of or the entire uvea. "Our proof-of-concept study demonstrates that blocking IL-7 or IL-15 leads to specific depletion of the uveitogenic memory CD4+ T cells and disruption of disease chronicity in uveitis." (PMID 40323267, 2025).
vasculitis (1 paper, 2012). "Further studies, therefore, will be required to determine the role of human T lymphocytes in the pathogenesis of vasculitis in this mouse model, by generating chimeras and administering IL7-Fc, It is interesting to note, nevertheless, that vasculitis developed in the presence of very few T cells." (PMID 22247758, 2012).
WHIM syndrome (1 paper, 2024). "Less frequent findings included cases of the WHIM syndrome, SYKgain-of-function, and IL-7 deficiency." (PMID 39836844, 2024).
xerostomia (1 paper, 2023). Dryness of the mouth resulting from reduced salivary secretion. "Among the inflammatory cytokines assessed - IL-6, TNF-α, IFN-γ, IL-10, IL-12p70, IL-1β, IL-8, IL-13, IL-2, IL-5, IL-7 and IL-17A, xerostomia correlated with lower levels of saliva IL-2 and TNF-α, and elevated levels of serum IL-12p70 and IL-10 (p < 0.05)." (PMID 36846089, 2023).
tumor (504 papers, 1998 to 2026). "BAG6-mediated immune modulation and IL-7's dual effects on tumor progression were also linked to poor survival." (PMID 40959273, 2025). "VV encoding interleukin-7 (IL-7) and IL-12 have been shown to activate immune responses, leading to complete tumor regression." (PMID 40867310, 2025). "Among the novel OVs being developed, the encoding of specific cytokines to stimulate tumor immune responses is an important research direction, with IL-7, IL-12, IL-15, and others representing key candidates." (PMID 40001666, 2025). "We generated trifunctional antibody-cytokine fusion proteins composed of a scFv antibody directed against the fibroblast activation protein (FAP) as a tumor associated model antigen, IL-15 fused to an IL-15Rα fragment (RD), and either IL-7 or IL-21." (PMID 40370435, 2025). "Interleukin-7 (IL-7), acting via the IL-7 receptor (IL-7R), plays a significant role in tumor progression, is closely associated with a poor prognosis for patients with PC, and is associated with MMP-3 and MMP-7 expression." (PMID 40001606, 2025). "Compared with both placebo and antigen-only vaccines, co-encoded antigen + IL-7 vaccines improved tumor control and survival endpoints." (PMID 41042672, 2025). "Pearson-r correlation between tumor volume and all immune signatures revealed significant association of higher IL-7 and IL-18 with reduced tumor growth." (PMID 40386779, 2025). "TILT-517 is an oncolytic adenovirus encoding interleukin-7, designed to selectively target tumor cells and stimulate the tumor microenvironment." (PMID 40589567, 2025). "We also observed the expression of IL-7 and IL-7R in various mouse and human cell types and tumor tissues, which suggests that targeting the IL-7/IL-7R pathway presents both an opportunity and a risk for cancer patients." (PMID 38424167, 2024). "TLS development starts when APCs deliver tumor-associated antigens to adaptive immune cells, resulting in lymphocyte activation and cytokine secretion [e.g., Interleukin-7(IL-7)]." (PMID 38333212, 2024). "The IL-7 gene vaccine is a gene therapy that enhances anti-tumour immune responses by introducing the IL-7 gene into tumour cells or immune cells to cause them to produce the IL-7 protein, thereby increasing IL-7 levels." (PMID 38675377, 2024). "In this study, we generated lipid nanoparticle (LNP)-encapsulated cytokine mRNAs encoding IL-12, IL-7, and IFN-α as anti-tumor drug candidates and evaluated the therapeutic benefits of intratumoral administration of IL-12/IL-7/IFN-α triplet." (PMID 39290693, 2024). "In this study, a dual therapy involving tumor stroma–binding IL-7 and IL-12 variants is used to guide the design of next-generation immunotherapy combinations, which lead to synergistic antitumor efficacy without compromised tolerability." (PMID 38019919, 2023). "IL-7 is closely associated with tumor development and has been used in clinical research and treatment." (PMID 36142322, 2022). "The use of tumor-selective oncolytic vaccinia viruses encoding interleukin-7 (IL-7) and interleukin-12 (IL-12) can make mice with complete tumor regression resist the re-attack by the same tumor cells." (PMID 35719333, 2022). "For instance, IL-7, a pleiotropic cytokine, has been proved to be associated with lymph node involvement and tumor location of CRC." (PMID 36313449, 2022). "IL-7 is closely associated with tumor development and has been used in cancer clinical research and therapy." (PMID 36142322, 2022). "In brief, the shift from a Th1 to a Th2 inflammatory response will lead to an increase in immunosuppressive cytokine release (IL-2, IL-4, IL-7, IL-13, and IL-15) by neoplastic elements and tumor-associated cells, sustaining tumor growth and spread." (PMID 34685762, 2021). "Partial correlation coefficient (rp) for the net association between IL-7 overexpression and tumor location in the stomach was 0.51." (PMID 31185636, 2019).
tumor (continued). "Tumor location in the colorectum was found independently associated with IL-7 concentration in tumor tissue, explaining 22% of variability in its variability." (PMID 31185636, 2019). "Even with those differences accounted for, tumor location (p = 0.004) was significantly associated with systemic IL-7 concentrations." (PMID 31185636, 2019). "Tumor location in the colorectum was independently associated with IL-7 concentration in macroscopically normal tissue adjacent to the tumor, explaining 27% in its variability." (PMID 31185636, 2019). "For instance, exogenous IL-7 treatment enhances cytotoxic CD8 T cell anti-tumor activity and reverses T cell exhaustion caused by chronic LCMV infection, and thus, preventing liver pathology." (PMID 31921158, 2019). "Of these, tumor location in the stomach alone was significantly associated with IL-7 overexpression, explaining 26% variability in IL-7 fold change." (PMID 31185636, 2019). "The difference was caused by a significant difference in IL-7 concentration in macroscopically normal tumor-adjacent tissue: significantly higher in Stage 1/2 than Stage 3/4 cancers." (PMID 31185636, 2019). "Nevertheless, this set of experiments demonstrates that the loss of Il7-expressing CAFs impinges on tumor cell stemness in vivo, suggesting that these cells form a genuine niche for breast CSC maintenance." (PMID 29632733, 2018). "Il7-expressing breast CAFs were spatially associated with the tumor microvasculature and directly interacted with BC cells, presumably engaging in reciprocal signaling circuits." (PMID 29632733, 2018). "This was associated with both increased IL-1 and IL-7, Th1 cytokines (which favor anti-tumor cytotoxic T lymphocytes), as well as enhanced doxorubicin-induced reduction of Th2 cytokines (which prevent tumor rejection and promote tumor growth)." (PMID 26828520, 2016). "Increased expression of IL-7R was also found to prevent apoptosis and promote proliferation and migration of tumor cells by activating intracellular pathways and upregulating the associated downstream molecules via binding to its ligand, IL-7." (PMID 27821177, 2016). "An additional promising approach demonstrated that exogenous IL-7 added to T cells co-cultured with tumor cells inhibited loss of CD28, a feature of replicative senescence, and allowed normal proliferative capacity and IL-2 production." (PMID 27809856, 2016). "This shift is characterized by increased protein expression of IL-2 and IL-7, suppressed recruitment of tumor-associated macrophages, myeloid derived suppressor cells, T regulatory cells, and decreased tumor angiogenesis and lymphangiogenesis." (PMID 19956757, 2009). "In fact, it has been previously demonstrated that T and B cells produce IL-7, in both tumours and other pathologies associated to bone resorption." (PMID 18978943, 2008). "Although higher viral titers can contribute to oncolysis, the expression of GM-CSF and IL-7 may have additionally influenced the tumor cells’ susceptibility to viral killing." (PMID 40299475, 2025). "Finally, to address the challenge of sustaining T cell responses, we developed vaccines that co-encode the cytokine signal IL-7 and demonstrate improved memory formation and tumor control." (PMID 41042672, 2025). "Likewise, a combinatorial study using tumor matrix (collagen)-binding IL-7 and IL-12 showed synergistic antitumor effects associated with the induction of immunologic memory." (PMID 40957993, 2025). "Additionally, high NLR has been associated with elevated infiltration of tumour-associated macrophages in the tumour microenvironment and elevated circulating cytokines (IL-1ra, IL-6, IL-7, IL-8, IL-9, IL-12, IFN-γ, IP10, MCP-1, MIP-1β, and PDGF-BB)." (PMID 36077723, 2022). "In PEs, the association of high IL‐7 levels with lower survival of patients could be related to the tumor development." (PMID 36054746, 2022).